CTXN2 (cortexin 2)
Tractability: Antibody: UniProt predicts a signal peptide or a membrane-spanning region.
Gene: Protein-coding gene on chromosome 15 (48,177,875 to 48,203,758, forward strand). Ensembl gene ENSG00000233932.
Subcellular location: Membrane
Gene Ontology:
Cellular component: membrane
Genetic constraint (gnomAD): Loss-of-function variants: 3 observed, 5.97 expected, observed/expected ratio (o/e) 0.5, 90% interval 0.23 to 1.29. That is too few expected variants to judge how well the gene tolerates losing a copy. Missense variants: 87 observed, 97.05 expected, observed/expected ratio (o/e) 0.9, 90% interval 0.75 to 1.07. Synonymous variants: 38 observed, 38.5 expected, observed/expected ratio (o/e) 0.99, 90% interval 0.76 to 1.29.
Homologues: Orthologues: chimpanzee CTXN2 (100% identical), dog CTXN2 (100% identical), macaque CTXN2 (100% identical), rabbit CTXN2 (100% identical), guinea pig CTXN2 (99% identical), pig CTXN2 (96% identical), mouse Ctxn2 (95% identical), rat Ctxn2 (95% identical). Paralogues in human: CTXN3 (51% identical), CTXN1 (42% identical).
Diseases named in the same sentence as CTXN2 in open-access papers:
CTXN2 is named in the same sentence as 1 disease in open-access papers, as found by Europe PMC text mining. Sharing a sentence is not in itself a finding about the gene and the disease. The quoted sentences say what the papers report.
partial albinism (1 paper, 2022). "For example, SLC24A5, MYEF2, and CTXN2 gene variations have been associated with differences in skin pigmentation, partial albinism, and retinal pigment; SLC12A1 plays a key role in concentrating urine, and its defects result in some Bartter-like syndromes." (PMID 35440892, 2022).